SETBP1 (SET binding protein 1)
Diseases named in the same sentence as SETBP1 in open-access papers (continued):
Sharing a sentence is not in itself a finding about the gene and the disease.
breast carcinoma (7 papers, 2015 to 2023). "SETBP1 mutations have also been identified in solid tumors including pancreatic neuroendocrine tumors, breast cancer, non‐small cell lung cancer, and gastric cancer." (PMID 37489294, 2023). "It has also been reported that SETBP1 expression decreases in the stroma as breast cancer progresses from grades I to III." (PMID 37489294, 2023). "SET binding protein 1 (SETBP1), known as PP2A phosphatase activity inhibitor, was implicated in cancer pathogenesis such as leukemic malignancies, colorectal cancer, lung cancer, and breast cancer." (PMID 35125116, 2022). "Moreover, SETBP1 was identified as an oncogene contributing to breast cancer development." (PMID 35898891, 2022). "Furthermore, miR-211-5p could serve as a potential therapeutic target via targeting SETBP1 or SIRT1 for breast cancer." (PMID 34151707, 2021). "Therefore, it remains necessary to analyze whether SET is proteolyzed in breast cancer before concluding that SETBP1 could contribute to PP2A inhibition in this disease." (PMID 25726524, 2015). "Moreover, the authors studied publically available datasets (cBioPortal) and reported that PP2A activation status could be deregulated in more than 50% of basal breast cancer tumors due to alterations affecting PP2A subunits or deregulation of endogenous PP2A inhibitors such as SETBP1, SET or CIP2A." (PMID 25726524, 2015).
epilepsy (7 papers, 2017 to 2024). A brain disorder characterized by episodes of abnormally increased neuronal discharge resulting in transient episodes of sensory or motor neurological dysfunction, or psychic dysfunction. "This is the case of the SETBP1 germline variant p.Glu858Lys, reported as somatic in myeloid malignancies, which we identified in a girl with severe ID and drug resistant epilepsy and found to be de novo in her reportedly unaffected mother." (PMID 33391157, 2020). "Additionally, the prominent clinical manifestation of case 3 was epilepsy, which is reported in 95% of the SGS patients with hot spot mutations, and frequently observed also in patients with SETBP1 haploinsufficiency." (PMID 33391157, 2020). "Disease pathways identified were consistent with the core phenotypes characteristic of SETBP1-HD including language delay, autism, ADHD, delayed development, and epilepsy." (PMID 39350244, 2024).
intellectual disability, autosomal dominant 29 (7 papers, 2021 to 2025). "The LOF mutation is called SETBP1 haploinsufficiency disorder through the haploinsufficiency mechanism, and is also named as intellectual disability, autosomal dominant 29 (MRD29, OMIM #616078)." (PMID 41282480, 2025). "Variants of SETBP1 can cause mental retardation, autosomal dominant 29 (MRD29), also known as SETBP1 disorder, which is a condition that involves mental retardation, speech and language problems, and non-specific facial features." (PMID 37798664, 2023). "Intellectual disability, autosomal dominant 29 is a rare disorder resulting from pathogenic variants of SETBP1 gene with no specific mutation hotspot identified." (PMID 40144891, 2025).
juvenile myelomonocytic leukemia (6 papers, 2016 to 2021). A myelodysplastic/myeloproliferative neoplasm of childhood that is characterized by proliferation principally of the granulocytic and monocytic lineages. "Moreover, SETBP1 mutations have been occasionally described in juvenile myelomonocytic leukemia (JMML) and in about 1.7%–7% of sAML arising from MPN or MDS." (PMID 34858828, 2021). "The difference in molecular consequences between somatic and germline SETBP1 mutations is in line with findings from previous studies examining somatic and germline mutations in PTPN11, involved in juvenile myelomonocytic leukemia and in Noonan syndrome, respectively." (PMID 28346496, 2017). "For example, it is known that PP2A can regulate the RAS-MAPK pathway via dephosphorylation of several substrates; this interplay could explain the presence of SETBP1 mutations in the pathogenesis of Juvenile Myelomonocytic Leukemia (JMML), which is mainly believed to be a RAS driven disease." (PMID 28881700, 2017).
lung cancer (6 papers, 2020 to 2024). A malignant neoplasm involving the lung. "In non‐small cell lung cancers, decreased SETBP1 expression has been reported to cause epithelial‐mesenchymal transition and cell proliferation via ERK signaling." (PMID 37489294, 2023).
myeloid leukemia (6 papers, 2016 to 2024). A clonal proliferation of myeloid cells and their precursors in the bone marrow, peripheral blood, and spleen. "According to the literature, both the overexpression of SETBP1-WT and the presence of missense mutations would activate SETBP1 to promote tumorigenesis in myeloid leukemia." (PMID 39054337, 2024). "SETBP1 somatic mutations were well studied in many clonal myeloid disorders and associated with poor outcomes in myeloid leukemia." (PMID 37356061, 2023). "On the other hand, MYB expression is known to be critical for myeloid leukemia induced by SETBP1 activation, and its inhibition could be beneficial for treating SETBP1-associated neoplasms." (PMID 38165902, 2024). "Consistent with our previous studies, two of the mice receiving wild-type Setbp1 transduced cells developed myeloid leukemia in 5 months and all mice receiving empty virus infected cells remained healthy during the same period." (PMID 27863435, 2016). "We have shown previously that myeloid leukemias induced by wild-type Setbp1 are transplantable." (PMID 27863435, 2016).
apraxia (5 papers, 2019 to 2026). Apraxia is a neurological disorder characterized by the inability to perform tasks or movements, despite having the desire and physical ability to perform them. "Along with mild to moderate ID, the most striking features associated with SETBP1 haploinsufficiency are speech defects in particular as expressive speech impairment or as severe oral dyspraxia." (PMID 33391157, 2020). "Typically, children with SETBP1-HD present with speech delay (first words by 18 months in 50%) due to a severe childhood apraxia of speech (CAS) (observed in 80%)." (PMID 38520002, 2024).
ovarian carcinoma (5 papers, 2022 to 2025). A malignant neoplasm originating from the surface ovarian epithelium. "VEZF1 has been implicated in the transcriptional activation of SETBP1, thereby promoting ovarian cancer progression." (PMID 40858565, 2025). "Furthermore, overexpression of tripartite motif-containing 29 (TRIM29) is closely associated with adverse clinical outcomes in ovarian cancer and promotes the proliferation, migration, and invasion of ovarian cancer cells via the SETBP1/SET/PP2A carcinogenic signal axis." (PMID 35898891, 2022). "For instance, a study showed that the SETBP1 pathway was regulated by TRIM29 to promote the progression of ovarian cancer, and SETBP1 overexpression acted as a poor prognosticator in gastric cancer." (PMID 37535001, 2023). "A recent study identified TRIM29 maintenance of CSCs-like characteristics in ovarian cancer through facilitated SETBP1 (SET Binding Protein 1) transcriptional activation and the downstream SET axis." (PMID 36261847, 2022). "Additionally, VEZF1 activates SETBP1 transcription, and the SETBP1/SET/PP2A oncogenic signaling axis promotes the malignant phenotype of ovarian cancer cells." (PMID 40858565, 2025). "SETBP1 has been identified as a key target of TRIM29, and the SETBP1/SET/PP2A axis has been shown to be essential for the progression of ovarian cancer driven by TRIM29." (PMID 39273321, 2024). "In addition, TRIM29 can facilitate SETBP1 transcriptional activation via the vascular endothelial zinc finger 1 (VEZF1) transcription factor, promoting ovarian cancer progression." (PMID 35898891, 2022).
anemia (3 papers, 2022 to 2024). A reduction in the number of red blood cells, the amount of hemoglobin, and/or the volume of packed red blood cells. "On a side note, HSCT therapy is highly recommended for patients with poor prognostic factors, e.g., significant anemia, a high burden of blasts, and mutations associated with increased mortality, such as SETBP1 and ASXL1." (PMID 35949766, 2022). "Compared to patients with wild−type SETBP1, those harboring SETBP1 mutations have significantly elevated WBC counts, more severe thrombocytopenia and anemia, as well as more pronounced cellular dysplasia." (PMID 38992589, 2024). "Our whole body SETBP1 overexpressing mouse dies early in utero for anemia." (PMID 37270547, 2023).
Obesity (3 papers, 2018 to 2025). Accumulation of substantial excess body fat. "Differential DNA methylation of a site linked to SETBP1 has previously been associated with obesity." (PMID 39623445, 2024). "In the obesity signature, eight genes were found to possess regulatory functions: COPS5, GATA2, MORF4L1, OPTN, PFDN5, SETBP1, TCF4, and ZBTB16." (PMID 40102990, 2025). "SETBP1, which encodes the SET-binding protein 1, seems not to have been associated with obesity previously." (PMID 30397228, 2018).
schizophrenia (3 papers, 2021 to 2025). A major psychotic disorder characterized by abnormalities in the perception or expression of reality. "Variants in NDST4 were associated with ASD, variants in RORB were associated with childhood autism, and variants in SETBP1 were associated with schizophrenia." (PMID 34773992, 2021). "Tests for three genes obtained nominally significant p values: NDST4 in ASD, RORB in childhood autism, and SETBP1 in schizophrenia." (PMID 34773992, 2021). "Our TWAS also identified genes previously associated with cognitive domains, neuropathology, and psychiatric illness, including reading-related skills and neural structures (SEMA6D and SETBP1), working memory tasks (CDH13), and Schizophrenia (HP, C18orf1, and TMEM180)." (PMID 40141087, 2025). "Interestingly, one gene, SETBP1, has been implicated in both DLD60 and schizophrenia, but PGS-based analyses have not found a significant overlap between the disorders." (PMID 39468758, 2025).
autism (2 papers, 2021 to 2024). Persistent deficits in social interaction and communication and interaction as well as a markedly restricted repertoire of activity and interest as well as repetitive patterns of behavior. "Other neural symptoms consistent with SETBP1-HD phenotype include hyperkinesia in ADHD; sensory changes in autism; dysmorphic facial features, ophthalmological abnormalities such as retinopathy; and alterations in digestion related pathways." (PMID 39350244, 2024).
B-cell lymphoma (2 papers, 2020 to 2021). "Further, SETBP1 expression also correlated with increased staging of the TBCL samples (r = 0.66), indicating its potential as B-cell lymphoma marker in multiple subtypes." (PMID 32457837, 2020).
colorectal cancer (2 papers, 2022). A primary or metastatic malignant neoplasm that affects the colon or rectum. "It has also been reported that SETBP1 expression is similar or lower in colorectal cancer tissue compared to normal colonic mucosa." (PMID 35898891, 2022).
developmental and epileptic encephalopathy (2 papers, 2020 to 2023). An epilepsy associated with developmental impairment that may be due to either the underlying etiology or the superimposed epileptic activity, or both. "Our findings contribute to further characterizing the associated phenotypes and suggest inclusion of SETBP1 in the list of prioritized genes for the genetic diagnosis of overlapping phenotypes ranging from non-specific ID to “developmental and epileptic encephalopathy” (DEE)." (PMID 33391157, 2020). "Our findings support the inclusion of SETBP1 in the list of prioritized genes for the genetic diagnosis of overlapping phenotypes ranging from non-specific NDDs to “developmental and epileptic encephalopathy” (DEE)." (PMID 33391157, 2020). "In order to estimate the contribution of SETBP1 in phenotypes differing from classic SGS, we included SETBP1 in two NGS-targeted gene panels for the diagnosis of individuals with non-specific neurodevelopmental disorders (NDDs) or developmental and epileptic encephalopathy (DEE)." (PMID 33391157, 2020).
gastric cancer (2 papers, 2022 to 2023). A primary or metastatic malignant neoplasm involving the stomach. "SETBP1 is also involved in other cancer types, such as ovarian and gastric cancers." (PMID 37535001, 2023).
hydronephrosis (2 papers, 2017 to 2024). Collection of urine in the renal pelvis that results in dilatation of the renal pelvis and calyces. "Type II refers to as an intermediate phenotype of SGS, is diagnosed in patients with development delays and the distinctive facial features, but without the presence of hydronephrosis or typical skeletal abnormalities, with the presence of the SETBP1 variant." (PMID 38711130, 2024). "Both individuals carrying a mutation affecting SETBP1 residue S867 had the characteristic facial features of SGS, genital anomalies and seizures but no hydronephrosis." (PMID 28346496, 2017).
language disorder (2 papers, 2024). A category of disorders characterized by an impairment in the development of an individual's language capabilities, which is in contrast to his/her non-verbal intellect. "Individuals with SETBP1-HD may also present with a mild-to-moderate receptive language disorder." (PMID 38520002, 2024).
lung adenocarcinoma (2 papers, 2020 to 2022). A carcinoma that arises from the lung and is characterized by the presence of malignant glandular epithelial cells.
melanoma (2 papers, 2023 to 2024). A malignant, usually aggressive tumor composed of atypical, neoplastic melanocytes. "Kaplan-Meier results showed that SETBP1 mutated (SETBP1-MUT) melanoma patients exhibited a markedly improved ICI survival benefit than wild-type patients (median survival time: 49.3 vs. 25.6 months, Log-rank test P < 0.001)." (PMID 37535001, 2023). "We observed that SETBP1 mutated (SETBP1-MUT) melanoma patients exhibited significantly prolonged ICI survival outcomes compared to wild-type patients (HR: 0.56, 95% CI: 0.38-0.81, P = 0.002)." (PMID 37535001, 2023). "In this work, SETBP1 mutations were also identified to be linked with favorable ICI treatment outcomes in both melanoma and NSCLC." (PMID 37535001, 2023). "A waterfall plot was finished to show the concrete mutational pattern of SETBP1 mutations and their association with melanoma’s other driver genes and clinical factors." (PMID 37535001, 2023). "We further investigated the role of SETBP1 mutations in melanoma and NSCLC patients who received conventional chemotherapies from the TCGA." (PMID 37535001, 2023). "We also investigated the ICI prognostic roles of SETBP1 mutations in each melanoma cohort and the distinct therapeutic types used in this study (respectively)." (PMID 37535001, 2023). "Overall, our findings suggest that SETBP1 mutations may serve as a new biomarker for stratifying beneficiaries of ICI treatments in melanoma and NSCLC, which provides possible evidence for tailoring clinical immunotherapeutic strategies." (PMID 37535001, 2023). "Furthermore, we conducted an evaluation of the TMB distribution in distinct SETBP1 mutational statuses among melanoma and NSCLC cell lines derived from the CCLE project." (PMID 37535001, 2023). "We thus analyzed the connection of SETBP1 mutations with TMB in melanoma." (PMID 37535001, 2023). "We first explored the ICI prognostic roles of SETBP1 mutations in pooled melanoma patients." (PMID 37535001, 2023). "Moreover, gene set enrichment analysis showed that pro-inflammatory related T cell receptor signaling pathway (FDR = 0.016), B cell receptor signaling pathway (FDR = 0.014), and chemokine signaling pathway (FDR = 0.007) were all noticed in melanoma patients with SETBP1 mutations." (PMID 37535001, 2023). "Further analysis based on samples from the TCGA cohort revealed significantly reduced SETBP1 expression in the SETBP1 mutant subgroup in both melanoma (Wilcoxon rank-sum test P = 0.034) and NSCLC (Wilcoxon rank-sum test P = 0.008)." (PMID 37535001, 2023). "We consistently observed strong associations between SETBP1 mutations and increased TMB in both tumors (Wilcoxon rank-sum test P = 0.028 and 0.013 for melanoma and NSCLC, respectively)." (PMID 37535001, 2023). "Survival analysis indicated that there was no significant survival difference between SETBP1 two groups (multivariate Cox P = 0.143) in melanoma; however, a significantly preferable prognosis was observed in SETBP1-MUT NSCLC patients (multivariate Cox P = 0.043)." (PMID 37535001, 2023). "In melanoma, based on the lymphocyte infiltration methods, we observed more infiltration of immune-promotion cells (e.g., CD8 T cells and M1 macrophages) and less infiltration of immune-suppressive cells (e.g., regulatory T cells) in the SETBP1-MUT subgroup (all P < 0.05)." (PMID 37535001, 2023).
Miller syndrome (2 papers, 2018 to 2021). "Some examples of new disease-associated genes that have been discovered using NGS technologies are DHODH, the causative gene of the Miller syndrome, WDR35, the gene that is responsible for Sensenbrenner syndrome, and SETBP1, which is responsible for the Schinzel–Giedion syndrome (SGS)." (PMID 34827709, 2021).
non-small cell lung carcinoma (2 papers, 2022). A group of at least three distinct histological types of lung cancer, including non-small cell squamous cell carcinoma, adenocarcinoma, and large cell carcinoma. "The downregulation of SETBP1 expression has been reported to promote non-small cell lung cancer progression by inducing cellular epithelial-mesenchymal transition (EMT) and disordered immune status." (PMID 35898891, 2022). "It was reported that decreased expression of SETBP1 contributed to the development of non-small-cell lung cancer cells by increasing tumor cell proliferation, migration, and invasion and was associated with poor prognosis." (PMID 35433683, 2022). "Conversely, lower SETBP1 expression was found to promote non-small cell lung cancer progression by inducing cellular EMT and disordered immune status." (PMID 35898891, 2022).
Thrombocytopenia (2 papers, 2022 to 2024). A reduction in the number of circulating thrombocytes. "In the pre-PMF group, we found that thrombocytopenia, ASXL1, MPL, U2AF1, SETBP1, and SRSF2 mutations were associated with inferior overall survival." (PMID 36139644, 2022).
acute lymphoblastic leukemia (1 paper, 2017). Leukemia with an acute onset, characterized by the presence of lymphoblasts in the bone marrow and the peripheral blood. "Indeed, SETBP1 mutations do not seem to be involved in the leukemogenesis of acute lymphoblastic leukemia (ALL) and childhood AML." (PMID 28881700, 2017).
amyotrophic lateral sclerosis (1 paper, 2023). Amyotrophic lateral sclerosis (ALS) is a neurodegenerative disease characterized by progressive muscular paralysis reflecting degeneration of motor neurons in the primary motor cortex, corticospinal tracts, brainstem and spinal cord. "A subset of our organoid datasets come from studies that performed diverse perturbations (22q11.2 deletion, SMARCB1 knockdown, exposure to Alzheimer’s serum, SETBP1 point mutations, amyotrophic lateral sclerosis patient-derived organoids)." (PMID 37034757, 2023).
androgenetic alopecia (1 paper, 2025). "Variants within the 3′ region of SETBP1 have been associated with early-onset androgenetic alopecia in human patients." (PMID 40725390, 2025).
Ataxia (1 paper, 2023). Ataxia refers to impaired coordination of voluntary muscle movement. "A pattern of CAS alongside dysarthria is not uncommon in other genetic forms of persistent speech disorder, for example in Koolen de Vries Syndrome, SETBP1-haploinsufficiency disorder, or EBF3-related core motor disturbance and ataxia." (PMID 36117209, 2023).